TNF (tumor necrosis factor)
Diseases named in the same sentence as TNF in open-access papers (continued):
Sharing a sentence is not in itself a finding about the gene and the disease.
Impaired glucose tolerance (54 papers, 2009 to 2025). An abnormal resistance to glucose, i.e., a reduction in the ability to maintain glucose levels in the blood stream within normal limits following oral or intravenous administration of glucose. "Mice subjected to a diet containing polystyrene MPs over an 8‐week period displayed increased serum TNF‐α levels along with impaired glucose tolerance." (PMID 41498107, 2025). "Shows weight gain, lipid inflammation, and impaired glucose tolerance.Increased amount of tumor necrosis factor-α mRNA and impaired glucose homeostasis in PCB-77-exposed mice after weight loss." (PMID 38251002, 2024). "Some studies have shown higher TNFα and lower IL-10 levels associated with increased HbA1c in patients with T2DM and DPN than in patients with impaired glucose tolerance and healthy controls." (PMID 32825324, 2020). "Previously, Watkins and Sinclair (2014) reported that the adult offspring from LPD-fed fathers developed impaired glucose tolerance and increased serum TNF-α level." (PMID 31289120, 2019). "Elevated blood sugar levels lead to increased circulating levels of cytokines such as IL-6, TNF-α, and IL-18, which may contribute to impaired glucose tolerance even in healthy individuals through oxidative mechanisms." (PMID 41011276, 2025). "Possible mechanisms proposed to be involved include inflammatory processes, as research has linked experimentally raised glucose levels with increased plasma cytokine levels (tumor necrosis factor-α, interleukin-6 and interleukin-10) in healthy individuals and those with impaired glucose tolerance." (PMID 24023897, 2013). "This is surprising since, although metformin did not decrease circulating levels of C reactive protein and cell adhesion molecules in subjects with impaired glucose tolerance, it reduced the TNFα-induced activation of NFκB and secretion of VCAM-1 and MCP-1 in vascular endothelial cells." (PMID 19317897, 2009). "Nevertheless 7 subjects had detectable elevated CRP and 7 had elevated TNFα, all of whom reduced their levels post study, implying reduced inflammation associated with adiposity Three subjects did have impaired glucose tolerance (IGT) which normalized post-study independent of weight changes." (PMID 30785891, 2019). "They showed that TNF-α positively correlated with FPG and fasting plasma insulin in normal glucose tolerance and impaired glucose tolerance subjects." (PMID 36140983, 2022). "After 12 weeks of Eriomin supplementation with 200, 400, or 800 mg per day, there was a significant decrease in fasting glycemia, impaired glucose tolerance, HOMA‐IR, HbA1c, glucagon, C‐peptide, hsCRP, IL‐6, and TNF‐α." (PMID 31183921, 2019). "Consistent with significantly increased TNFα protein and mRNA levels in adipose tissue, HF-EFA fed rats had impaired glucose tolerance compared to HF-AFA fed rats." (PMID 27669293, 2016). "Feeding a red algae (GA) diet has been shown to significantly decrease plasma TNF-α, leptin, and TC/TG levels, but not affect the weights of body, liver, and adipose tissue, in a high fructose diet-impaired glucose tolerance rat model." (PMID 31540318, 2019). "Since we enrolled pre-DM subjects with impaired glucose tolerance (IGT) and without any other medical conditions we possibly did not observe elevated TNFα level." (PMID 26300782, 2015). "In female Turkish subjects, subjects with impaired glucose tolerance had higher fasting serum TNF-α levels than subjects with normal glucose tolerance (p < 0.01), and serum TNF-α and IL-6 concentrations were elevated during the glucose challenge (for each comparison, p < 0.01)." (PMID 21663637, 2011).
polyarthritis (54 papers, 2008 to 2025). "Similarly, docetaxel has recently been reported to reduce disease progression and joint destruction in rat polyarthritis models, an effect associated with the suppression of key inflammatory cytokines like TNF-α and IL-1β." (PMID 41614803, 2025). "Indeed, overexpression of only TNF-α was sufficient enough to cause chronic severe erosive polyarthritis resembling RA in mice transfected with human TNF-α gene engineered for enhanced transcription." (PMID 33581710, 2021). "A 70-year-old woman with long-standing seropositive, nodular rheumatoid arthritis was commenced on adalimumab, a tumor necrosis factor- α (TNF-α) inhibitor for polyarthritis despite treatment with methotrexate and leflunomide." (PMID 40585451, 2025). "Loss of DNase II activity results in the accumulation of host DNA in the cytosol, which subsequently triggers inflammatory polyarthritis with the production of inflammatory cytokines such as TNF-α, IL-1β, and IL-6." (PMID 37354378, 2023). "The STING S365A mutant, on the other hand, retains the ability to recruit TBK1 and activate NF-κB, and DNase II-/-STING-S365A mice developed severe polyarthritis, which was alleviated by neutralizing antibodies against TNF-α or the IL-6 receptor." (PMID 37354378, 2023). "TNF-Tg mouse is a RA transgenic mouse with chronic and persistent overexpression of human TNF-α and pathological manifestations of symmetry and polyarthritis." (PMID 35600883, 2022). "We evaluated ADA formation against each of the anti-TNFα antibodies and the efficacy of long-term administration of these anti-TNFα antibodies against the TNFα-mediated polyarthritis in Tg197 mice." (PMID 35273620, 2022). "In one of these four, the interruption of TNF-α inhibitor treatment (etanercept) resulted in a polyarthritis crisis; the drug was therefore reintroduced." (PMID 31684103, 2019). "In contrast, corticosterone was able to protect against the reduction in trabecular number in this model of inflammatory polyarthritis (Tb.N: TNF-tg/vehicle, 0.0004 1/μm ± 0.00002 vs TNF-tg/corticosterone, 0.00083 1/μm ± 0.00002, P < 0.0001)." (PMID 31370858, 2019). "In this study, we use the TNF-tg model of polyarthritis and wild-type (WT) counterparts to examine the effects of orally administered anti-inflammatory GCs on bone and muscle metabolism in the context of systemic inflammation." (PMID 31370858, 2019). "TNF transgenic (Tg) mice, which constitutively express human TNF, spontaneously develop inflammatory, highly erosive polyarthritis, similar to human RA, which can be completely prevented by treatment with monoclonal antibodies against human TNF." (PMID 30837986, 2019). "Intrathecal effects of TNF-blockade on CSF proteome in patients with polyarthritis at the baseline and after 8 weeks of infliximab treatment (n = 7) were investigated." (PMID 30770760, 2019). "In conclusion, using proteomic profiling of CSF in polyarthritis, we have identified several intrathecal proteins with known inflammatory and/or neuro-immune function that were affected by TNF-blocking treatment." (PMID 30770760, 2019). "The TNF-tg mouse is a murine model of polyarthritis driven by the transgenic overexpression of the pro-inflammatory cytokine TNFα that proved valuable in the initial validation of anti-TNFα biologicals." (PMID 31370858, 2019). "Unfortunately, as opposed to administration of infliximab in hTNFtg animals, clinical signs of polyarthritis were still evident, indicating that regular infliximab injections were unable to completely abrogate host murine TNFα overexpression." (PMID 28480797, 2018). "Synovial cells also respond to TNF-α in order to generate IL-1β and IL-6, trigger the expression of TNF-α gene, and consequently produce cytokines in the joint, which can result in polyarthritis development." (PMID 30083153, 2018).
polyarthritis (continued). "Transgenic tumour necrosis factor alpha (TNFα)-driven models of polyarthritis such as the TNFΔARE mouse have proven to be invaluable in delineating aspects of inflammatory disease pathophysiology in humans." (PMID 28480797, 2018). "Bivalent constructs of VHH#1 and VHH#3, which recognize completely different epitopes on the cytokine, were tested in the Tg197 transgenic human TNF model for polyarthritis, in which mice constitutively produce the human cytokine and develop acute arthritis." (PMID 28824615, 2017). "The other had partial response to prednisone, azathioprine, and TNF inhibition; thus, his anti-TNF biologic was recently switched to tocilizumab due to persistent polyarthritis." (PMID 29041934, 2017). "In the synovial tissue of human TNF-α transgenic mice that developed chronic inflammatory and destructive polyarthritis, the expression of p-ERK and p-p38 increased in macrophages along with the increased expression of p-ERK in fibroblasts, whereas p-JNK did not significantly change." (PMID 35755835, 2022). "To examine the contribution of 11β-HSD1 towards protective actions of GCs in a murine model of chronic inflammation, we utilised the TNF-tg model of chronic polyarthritis receiving oral corticosterone (100 μg/mL) with global transgenic deletion of 11β-HSD1 (TNF-tg11βKO)." (PMID 35806338, 2022). "We found that DNase II−/−STINGS365A/S365A mice, but not DNase II−/−STINGΔCTT/ΔCTT or DNase II−/−STINGL373A/L373A mice, developed polyarthritis characterized by inflammation and bone erosion due to the production of inflammatory cytokines such as TNF-α and IL-6." (PMID 34901991, 2022). "However, the STING S365A mutant retains the ability to recruit TBK1 and activate NF-κB, and DNase II−/−STING-S365A mice exhibited severe polyarthritis, which was alleviated by neutralizing antibodies against TNF-α or IL-6 receptor." (PMID 34901991, 2022). "Inflammatory cytokines such as TNF-α, IL-1β, and IL-6 were major drivers of this polyarthritis." (PMID 34901991, 2022). "Therefore, a genetically modified TNFα-transgenic (TNFTG) mouse model, which over-expresses human TNFα and develops an erosive polyarthritis with many characteristics observed in RA patients, has been widely used in RA-related researches." (PMID 34750358, 2021). "In the current work, we investigate the effects of TNF blockade (infliximab) on CSF protein levels in patients with polyarthritis, and candidate protein relationships to clinical measurements of disease activity, peripheral inflammation, function and patient-reported outcomes." (PMID 30770760, 2019). "TNF-α production via macrophages can be responsible for the promotion of polyarthritis." (PMID 30083153, 2018). "In this study, we sought to investigate whether GILZ overexpression could antagonize TNF-α-induced arthritic inflammation and protect bone by using a TNF-α transgenic mouse, an animal model of RA that spontaneously develops polyarthritis." (PMID 28771604, 2017). "In these animals, overexpression of human TNF-α induces severe inflammatory polyarthritis." (PMID 24885217, 2014). "Bone metabolism was assessed in the TNF-tg model of polyarthritis treated with oral GC (corticosterone), in animals with global (TNF-tg11βKO), mesenchymal (including osteoblast) (TNF-tg11βflx/tw2cre) and myeloid (including osteoclast) (TNF-tg11βflx/LysMcre) deletion." (PMID 35806338, 2022). "Mice carrying a human TNF transgene develop chronic inflammatory polyarthritis, and the administration of an anti-TNF monoclonal antibody to these arthritic mice completely prevents disease development, suggesting a direct and critical role for TNF in the pathogenesis of polyarthritis." (PMID 33198301, 2020). "However, it was not until 1991 that studies on a transgenic mouse model of overexpressed human TNFα promoted the role of TNF in the development of polyarthritis and that anti-TNF therapies could be effective against the human disease." (PMID 28044081, 2016).
polyarthritis (continued). "These authors included randomized controlled assays, observational studies, and systematic reviews designed to evaluate the cost of anti-TNF drugs for the treatment of JIA, polyarticular arthritis, or juvenile rheumatoid arthritis." (PMID 38145114, 2023). "In addition, TNF-tg animals are develop symmetrical polyarthritis and synovial hyperplasia due to human TNF-α overexpression Importantly, EFL3 could prevent inflammatory progression and joint destruction in CIA and TNF-tg animal models, further supporting its use as a therapeutic drug to treat RA." (PMID 35475473, 2022). "In cerebrospinal fluid from patients with polyarthritis, a downregulation of CADM3 has been reported following TNF-α blockage." (PMID 36080454, 2022). "We have shown that mice overexpressing TNF, by carrying a human TNF transgene (hTNFtg mice) or by deletion of ARE elements in the endogenous Tnf gene (TNFΔARE mice), spontaneously develop chronic polyarthritis, with histological manifestations fully resembling human RA." (PMID 37014697, 2023). "Subsequently, using an FCA model, the extract decreased the serum levels of pro-inflammatory interleukin (IL)-1ß, IL-6, and tumor necrosis factor-alpha (TNF-α) and increased the anti-inflammatory IL-10 levels in the synovial fluid of mice with untreated polyarthritis." (PMID 36903951, 2023). "In contrast to bone loss, oral GCs increased muscle wasting and did not restore animal mobility in the TNF-tg model of polyarthritis, despite effective suppression of disease activity." (PMID 31370858, 2019). "In case of predominant polyarticular arthritis (PA) and in case of lack of response to IL-1 or IL-6 inhibition, TNF-blockers were applied." (PMID 29622022, 2018). "During the course of the disease, for patients who have persistent polyarthritis without systemic inflammation, treatment with tumor necrosis factor-alpha (TNF) blockade or abatacept is an option." (PMID 29357887, 2018). "In our MTX-refractory ERA category, after TNF-α inhibitor treatment, only 30% attained a non-active disease status; this was lower than in the non-ERA MTX-refractory polyarthritis JIA (remission group = 52%) from our previous study." (PMID 31443722, 2019).
respiratory infection (54 papers, 2013 to 2026). "Patients under therapeutic treatment with biologics should receive information about susceptibility to respiratory infections, especially in terms of TNF-alpha inhibitors, because the rates are slightly increased." (PMID 39337940, 2024). "Common AEs associated with TNF-α and IL-12/IL-23 inhibitors use in children include injection site reactions, nasopharyngitis, mild upper respiratory infection (similar to those normally seen in children), and headache." (PMID 31590274, 2019). "Additionally, compared with the placebo group, anti-TNFα-treated patients showed a moderate increase in susceptibility to upper respiratory infections (URIs)." (PMID 37047412, 2023). "The vaccinations that elicited a significant level of protection against weight loss and infectious burden following an respiratory infection, induced secretion of the pro-inflammatory cytokine TNFα, IL-17 and IFNγ by splenocytes following in vitro re-stimulation with MOMP." (PMID 23613984, 2013). "This study corroborates the infection risk warnings for TNF-α inhibitors previously reported by Krabbe, while uniquely identifying clostridioides difficile infection as a predominant pediatric safety concern, contrasting with prior adult-focused studies emphasizing respiratory infections." (PMID 41329755, 2025). "As a classical probiotic, Lactobacillus has been associated with respiratory infections, able to enhance the body’s resistance to Spn infections and avoid excessive inflammatory damage by promoting an increase in IgA cells in the intestine and airways and regulating TNF-α and IL-10 balance." (PMID 37547684, 2023). "HCoV-OC43, a common human coronavirus, typically causes mild respiratory infections but can induce cytokine and chemokine responses in infected individuals, such as IL6, TNF-α, IL-8, CCL2 (MCP-1), and CCL5." (PMID 40872743, 2025). "While pro-inflammatory cytokines and type I interferons (IFNs) are important for antiviral defense, excessive tumor necrosis factor (TNF) is associated with severe disease in HMPV and other respiratory infections." (PMID 41346628, 2025). "Regarding anti-TNFα therapy, clinical trials showed a moderate increase in upper respiratory infections (UTRIs)." (PMID 37047412, 2023). "The mRNA expression of pro-inflammatory cytokines interleukin (IL)-1β and tumor necrosis factor (TNF)-α was decreased and an increased susceptibility to respiratory infections was suspected." (PMID 35159977, 2022). "At both day 7 and day 15 postintervention, the probiotics group had significantly lower levels of IL-6, IL-10, and tumor necrosis factor (TNF)-α, along with reduced hospital stays and lower rates of respiratory infection." (PMID 35203709, 2022). "TNF‐α was significantly higher in patients with COVID‐19 compared with non‐COVID‐19 respiratory infection (p < .01)." (PMID 35780481, 2022). "These genes are directly involved in innate immune sensing (TLR, MYD88, JAK/STAT), and inflammation (IL-6, IFN, TNF, IL-10, IL-22) which are two common host signaling pathways activated by bacteria and viruses during acute respiratory infections." (PMID 27532264, 2016). "Up-regulated proinflammatory cytokines, such as interleukin 1 (IL-1), IL-6 and tumor necrosis factor alpha (TNF-α), initiate this acute phase response and relate to intrinsic pathogenicity in the respiratory infection." (PMID 23637938, 2013). "However, at 7 dpi, monocytes/macrophages in the other animal (NV19) showed enrichment in pathways typically upregulated during a respiratory infection, such as TNF-⍺ and IL-6 signaling, and inflammatory response, complement, and coagulation." (PMID 39066335, 2024). "Of note, TNF-α was shown to exert protective efficacy in several models of respiratory infection." (PMID 26319657, 2015).